H2BK1 (H2B.K variant histone 1)
Description:
Core component of nucleosome. Nucleosomes wrap and compact DNA into chromatin, limiting DNA accessibility to the cellular machineries which require DNA as a template. Histones thereby play a central role in transcription regulation, DNA repair, DNA replication and chromosomal stability. DNA accessibility is regulated via a complex set of post-translational modifications of histones, also called histone code, and nucleosome remodeling.
Synonyms: H2BE1
Gene: Protein-coding gene on chromosome 7 (151,207,837 to 151,210,488, reverse strand). Ensembl gene ENSG00000285480.
Subcellular location: Chromosome; Nucleus
Gene Ontology:
Molecular function: DNA binding; structural constituent of chromatin; protein heterodimerization activity
Biological process: chromatin organization
Cellular component: chromosome; nucleosome; nucleus
Genetic constraint (gnomAD): Loss-of-function variants: 1 observed, 1.89 expected, observed/expected ratio (o/e) 0.53, 90% interval 0.17 to 1.77. That is too few expected variants to judge how well the gene tolerates losing a copy. Missense variants: 38 observed, 48.53 expected, observed/expected ratio (o/e) 0.78, 90% interval 0.6 to 1.03. Synonymous variants: 23 observed, 16.73 expected, observed/expected ratio (o/e) 1.38, 90% interval 0.98 to 1.85.
Homologues: Orthologues: macaque H2BK1 (99% identical), pig H2BK1 (91% identical), dog H2BK1 (89% identical), rabbit H2BK1 (88% identical). Paralogues in human: H2BC1 (70% identical), H2BC10 (69% identical), H2BC13 (69% identical), H2BC14 (69% identical), H2BC15 (69% identical), H2BC21 (69% identical), H2BC26 (69% identical), H2BC3 (69% identical), H2BC4 (69% identical), H2BC5 (69% identical), H2BC6 (69% identical), H2BC7 (69% identical), and 9 more.